TIMP1 (TIMP metallopeptidase inhibitor 1)
Diseases named in the same sentence as TIMP1 in open-access papers (continued):
Sharing a sentence is not in itself a finding about the gene and the disease.
metastatic disease (12 papers, 2011 to 2025). "Elevated CTC levels of 5 CTC/7.5 mL or more were only associated with the extend of metastatic disease, and elevated TIMP-1 and CAIX levels." (PMID 21745383, 2011). "When comparing both groups of patients (A versus B), we observed that patients with metastatic disease had higher expression of EV-derived TIMP-1 mRNA than patients with localized disease." (PMID 32610589, 2020). "We observed that patients with metastatic disease presented higher TIMP-1 EV mRNA levels compared to patients with localized disease (p = 0.002)." (PMID 32610589, 2020). "We observed that patients with metastatic disease and higher levels of TIMP-1 EV-derived mRNA presented a lower overall survival compared to patients presenting with lower levels (Log Rank test, p = 0.030)." (PMID 32610589, 2020). "The highest signal was from MMP-3 like it does in the metastatic tumors (mean IOD 28,600), followed by MMP-1 (mean IOD 20,200), MMP-9 (mean IOD 13,200), and TIMP-1 (mean IOD 12,300)." (PMID 27975070, 2016). "While studying the statistical significance of our evidence pointing out TIMP-1 as a participant in the process of metastasis, in this comparative study TIMP-1 has shown a tendency, involving its presence in metastatic tumors." (PMID 27975070, 2016). "We further studied the EV-derived mRNA expression of TIMP-1, TIMP-2 and MMP-1 mRNAs in plasma EVs from two groups of ccRCC patients: patients with localized disease before and after tumor removal surgery (Group A) and patients with metastatic disease (Group B)." (PMID 32610589, 2020). "Evaluation of expression of MMP-1, MMP-3, MMP-9, and TIMP-1 in 54 samples from patients with no metastatic tumors in lymph nodes was indirectly estimated by obtaining numeric values of intensity IOD, from the corresponding immunohistochemistry results (standard process)." (PMID 27975070, 2016). "TIMP-1 expression in primary and metastatic tumor tissue have not been compared, but usage of metastatic tumor tissue could potentially have had an impact on the results." (PMID 24884504, 2014). "In CAFs from metastatic tumors, a decrease in CCL2, MMP-2, TNC, OPN, and TGFβ levels and an increase in only TIMP1, PDPN, and SPP1 mRNA levels (without an effect on protein levels) was observed after calcitriol treatment." (PMID 38360633, 2024).
pancreatic ductal adenocarcinoma (12 papers, 2017 to 2025). An infiltrating adenocarcinoma that arises from the epithelial cells of the pancreas. "Other studies have found that TIMP-1 regulated by ERK2 causedhyperproliferation of KRAS pancreatic ductal carcinoma cells." (PMID 41002380, 2025). "Some studies reported that higher CXCL8 expression level was associated with shorter overall survival and relapse-free survival, TIMP1 gene is associated with poor prognosis of pancreatic ductal adenocarcinoma." (PMID 38313432, 2023). "Serum or urine levels of TIMP1 are also considered as a diagnostic predictor in pancreatic ductal carcinomas containing extensive desmoplasia." (PMID 30867991, 2019). "Several independent studies have reported TIMP-1 to be of prognostic and diagnostic value for pancreatic ductal adenocarcinoma (PDAC)." (PMID 29394913, 2018). "Blocking Timp1 expression with siRNA increased the sensitivity of pancreatic ductal adenocarcinoma cells to gemcitabine and reversed their resistance to chemotherapy; the combined action of shTIMP1 therapy and gemcitabine induced apoptosis of tumor cells." (PMID 36675165, 2023). "A similar observation has also been reported for pancreatic ductal adenocarcinoma, where exogenous addition of human recombinant TIMP‐1 significantly increased proliferation of pancreatic ductal cells, but only in KRAS‐transformed cells." (PMID 31545548, 2019). "Tissue inhibitor of metalloproteinases-1 (TIMP-1) is a candidate diagnostic and prognostic biomarker for pancreatic ductal adenocarcinoma (PDAC)." (PMID 29394913, 2018). "While it correlates with poor prognosis in pancreatic ductal adenocarcinoma (PDAC), TIMP1 also promotes neutrophil-mediated immune suppression, complicating therapeutic targeting." (PMID 40687427, 2025). "In vivo, biopsies from patients diagnosed with breast ductal carcinoma in situ (DCIS) and pancreatic ductal adenocarcinoma (PDAC) were immunostained with antibodies against TIMP-1 and CD82." (PMID 28030805, 2017). "TIMP-1 and CD82 expression status in patients with pancreatic ductal adenocarcinoma (PDAC) might demonstrate future usefulness as a differentiation marker and give us new insight into tumorigenic metastatic potential." (PMID 28030805, 2017). "Co-localization of TIMP-1 and CD82 observed in breast ductal carcinoma and pancreatic ductal adenocarcinoma may arise from this." (PMID 28030805, 2017).
acute kidney injury (11 papers, 2016 to 2025). Sudden and sustained deterioration of the kidney function characterized by decreased glomerular filtration rate, increased serum creatinine or oliguria. "A study indicated a correlation between septic shock and acute kidney injury (AKI), revealing that the genes PTX3, VMP1, OLFM4, SLPI, TIMP1, LCN2, and S100A9 are strongly correlated with novel biomarkers implicated in the onset and progression of sepsis‐associated acute kidney injury (SSAKI)." (PMID 41394771, 2025). "A study of children reported that elevated levels of urine TIMP-1 collected after admission to a pediatric intensive care unit might be an independent predictor of acute kidney injury and mortality." (PMID 38276268, 2023). "In patients, serum levels of TIMP-1 and TIMP-3 have been found to increase during the process of acute kidney injury, which has been suggested as a possible non-invasive marker of acute kidney injury." (PMID 40649789, 2025). "Sepsis may also induce acute kidney injury (AKI), and studies showed that VMP1, SLPI, PTX3, TIMP1, OLFM4, LCN2, and S100A9 genes were markedly correlated with the development and progression of septic-shock-associated AKI." (PMID 36299685, 2022). "In the rat renal failure model, UCG showed a renoprotective effect; it could promote extracellular matrix degradation and regulate MMP-2/TIMP-1 balance or signal molecular activity of the TGF-β/Smad pathway to alleviate renal dysfunction and tubulointerstitial fibrosis." (PMID 34678995, 2021). "In various models of acute kidney injury (AKI), which are mostly produced by renal ischemia-reperfusion injury, not only increased expressions of MMP-2, -9 and TIMP-2, but also decreased expression of TIMP-1 have been observed." (PMID 27455234, 2016).
Alzheimer disease (11 papers, 2010 to 2024). A progressive, neurodegenerative disease characterized by loss of function and death of nerve cells in several areas of the brain leading to loss of cognitive function such as memory and language. "TIMP1 has been shown to be elevated in the CSF of patients with both viral and bacterial meningitis, and also in the CSF of patients with Alzheimer’s disease, amyotrophic lateral sclerosis, Parkinson’s disease, and Huntington’s disease." (PMID 23185624, 2012). "Additionally, altered plasma levels of TIMP-1 have been detected in Alzheimer's disease and vascular dementia." (PMID 24391741, 2013).
astrocytoma (11 papers, 2015 to 2025). "The association between CD63 and TIMP-1 was investigated using previously obtained TIMP-1 data from our astrocytoma cohort." (PMID 29523123, 2018). "The aim of this study was to assess the prognostic impact of CD63 alone and in combination with TIMP-1 by performing immunohistochemistry on a cohort of 111 astrocytomas, described and used previously for evaluation of the prognostic potential of TIMP-1." (PMID 29523123, 2018). "To further investigate the influence of MMP-2 and TIMP-1 on tumor aggressiveness and prognosis in patients with astrocytomas, we evaluated mRNA expression levels in TCGA." (PMID 28234925, 2017). "Furthermore, it was found that there were specific binding sites of positive regulatory elements of nuclear factor kappa B (NF-κB) and ATF-2, which located the upstream the promoter region of TIMP-1 in the study of astrocytoma." (PMID 36690987, 2023). "To elucidate if the protein level in blood serum is related with the presence of brain tumours, we investigated the mRNA expression of TIMP-1, ANGPT1, SPP1 (OPN coding gene), IP-10, TGF-β1 and TIMP-1 in astrocytoma samples as well as in healthy human brain tissue." (PMID 34162919, 2021). "Here, applying decision tree classification algorithm we performed astrocytoma specific protein profile analysis on serum proteins TIMP-1, active and latent form of TGF-β1, IP-10, ANGPT-1, OPN, and YKL-40 using enzyme-linked immunosorbent detection assay (ELISA)." (PMID 34162919, 2021). "However, the expression level of TIMP1 is significantly higher in astrocytoma than oligodendroglioma and oligoastrocytoma." (PMID 30867991, 2019). "Herein, we tested the algorithm’s calculated for astrocytoma detection from blood serum and composed of active TGF-β1, TIMP-1 and YKL-40, ability to differentiate meningioma." (PMID 34162919, 2021). "Herein, as most promising protein profile for both low and high grade astrocytoma detection was composed of TGF-β1 active, TIMP-1 and YKL-40." (PMID 34162919, 2021). "The results demonstrated classification tree composed of three proteins—active TGF-β1, TIMP-1, YKL-40, and correctly classified 78.0% (103/132) of the whole sample, 71.7% (43/60) of healthy control sample and 83.3% (60/72) of astrocytoma sample." (PMID 34162919, 2021). "Results have demonstrated that astrocytoma specific profile consisted of three proteins—active form of TGF-β1, TIMP-1 and YKL-40 and was able to correctly classify 78.0% (103/132) of sample and 83.3% (60/72) of astrocytoma sample." (PMID 34162919, 2021). "TIMP-1, OPN, YKL-40, and active form of TGF-β1 protein levels in astrocytoma serum substantially differed from levels in healthy control group." (PMID 34162919, 2021). "We used data from GlioVis to detect the hub gene expression level between GBM and LGG including astrocytoma, oligodendroglioma, and oligoastrocytoma, the expression level of SAA1 and TIMP1 significantly increased in GBM." (PMID 30867991, 2019). "A profile with a relatively small number of proteins (ANGPT1, TIMP1, IP10, TGFβ1) was sufficient to correctly assign 79.7% (47/59) of the astrocytoma and 65.1% (28/43) of the control subjects." (PMID 31861636, 2019). "The aim of this study was to assess CD63 expression in astrocytomas focusing on the prognostic potential of CD63 alone and in combination with TIMP-1." (PMID 29523123, 2018). "The decision tree classification analysis was performed using “Classification Learner” application provided by MathWorks MatLab on TIMP-1, ANGPT-1, OPN, IP-10, TGF-β1 active, TGF-β1 latent and YKL-40 protein expression levels in astrocytoma patients and healthy control groups." (PMID 34162919, 2021). "TIMP-1, OPN, and latent form of TGF-β1 levels in astrocytoma differed from meningioma group." (PMID 34162919, 2021). "TIMP-1, ANGPT-1 and active form of TGF-β1 demonstrated the tendency of patient survival association with the lower protein level in astrocytoma, but the difference was not significant." (PMID 34162919, 2021).
astrocytoma (continued). "Here we showed that protein levels of TIMP-1, OPN, YKL-40, and active form of TGF-β1 in astrocytoma patient serum substantially differed as compared to control (healthy) group, while the differences between healthy control and meningioma group were observed only for ANGPT-1 and TGF-β1 active." (PMID 34162919, 2021). "Furthermore, prediction tree consisted of the same proteins as the astrocytoma detection algorithm that is TGF-β1 active, TIMP-1, YKL-40, with the addition of the protein of latent form TGF-β1." (PMID 34162919, 2021). "In conclusion, the serum protein profiles of ANGPT1, TIMP1, IP10, and TGFβ1 were associated with the presence of astrocytoma independent of its malignancy grade, while OPN and IP10 were associated with GBM patient survival." (PMID 31861636, 2019). "We examined the mRNA expression profiles of RECK transcripts, as well as of MMPs reportedly inhibited by canonical RECK (MMP-2, -9 and -14), and of endogenous tissue inhibitors of MMPs (TIMP-1, TIMP-2, TIMP-3 and TIMP-4) in astrocytomas of different grades of malignancy." (PMID 26431549, 2015).
bladder cancer (11 papers, 2006 to 2026). "Comparison of investigated enzymes’ activity and the inhibitor content suggests it opposite effects, higher suppression of MMP-14 than MMP-15 activity in low-grade bladder cancer and reverse TIMP-1 action in high-grade cancer." (PMID 32049862, 2020). "Comparison of investigated enzymes’ activity and the inhibitor content suggested it opposite effects, higher suppression of MMP-14 than MMP-15 activity in low-grade bladder cancer and reverse TIMP-1 action in high-grade cancer." (PMID 32049862, 2020). "Human urinary bladder cancer contains higher TIMP-1 amounts than control tissue but with the decrease with an increase in tumor grade." (PMID 32049862, 2020). "In this study, we found that urine from bladder cancer patients indicated the presence of 140 kDa MMP- 9/TIMP-1 complex but it was unfrequented in urine of those patients." (PMID 23672427, 2013). "In our study, MMP-9 was the most detectable gelatinases in the urine of bladder cancer patients which means a relative excess level of MMP-9 relative to TIMP-1 produced by the primary tumor and surrounding stroma." (PMID 23672427, 2013). "Decreased concentrations of TIMP-1 in plasma and increased concentrations in urine have been reported in bladder cancer." (PMID 22852097, 2012). "MMP2 is a statistically significant marker in blood plasma for bladder cancer detection with an increased diagnostic value in combination with MMP9 and TIMP1." (PMID 16901349, 2006). "The highest increase in TIMP-1 content was observed in low-grade urinary bladder cancer." (PMID 32049862, 2020). "But for the first time we could evaluate that MMP2 as a statistically significant marker in blood plasma for bladder cancer detection with an increased diagnostic value in combination with MMP9 and TIMP1." (PMID 16901349, 2006). "In addition, MMP9, MMP13, and TIMP1 are expressed in many bladder cancers and may mediate tumor invasiveness through extracellular matrix regulation." (PMID 23209855, 2012). "Taken together, our study detected many species of gelatinases in the urine of bladder cancer patients with primary tumor (both bilharzial and non bilharzial) including MMP-2, MMP-9, MMP-9 dimer, MMP-9/NGAL, MMP-9/TIMP-1 and ADAMTS-7." (PMID 23672427, 2013). "To further investigate whether hub genes have an impact on the prognosis of bladder cancer, we performed survival analysis of CXCL8, MDM2, TGFB2, FN1, TIMP1, and RPL22L1, and their impact on tumor stage using TCGA database." (PMID 34276798, 2021). "Receiver operating characteristic ROC curve analysis revealed that urinary TIMP-1 and serum NGAL may be useful non-invasive biomarkers to provide clinical information for bladder cancer disease." (PMID 30544619, 2018). "The results revealed that the measurement of TIMP-1 in plasma and/or urine was apparently not useful for the identification of bladder cancer." (PMID 22852097, 2012).
chronic kidney disease (11 papers, 2012 to 2025). Impairment of the renal function secondary to chronic kidney damage persisting for three or more months. "Second, we observed that chronic renal failure was associated to significantly lower day 3 MMP-8 levels and higher day 3 TIMP-1 levels." (PMID 34043679, 2021). "Patient demographics and underlying conditions had no impact on MMP-8 or TIMP-1 levels on day 3 or 5 with the exception of chronic renal failure that was associated to lower MMP-8 (p<0.05) and higher TIMP-1 (p<0.01) values." (PMID 34043679, 2021). "Accumulating data have shown that MMP-9 and TIMP-1 function differentially in chronic kidney diseases (CKDs)." (PMID 24396399, 2014). "Our study describes for the first time the disturbed Hsp27 concentrations, and the potential role of sFas/sFasL, MMP-7 and TIMP-1 in their regulation, in children with chronic kidney disease treated conservatively and on chronic dialysis." (PMID 22528051, 2012). "TIMP-1 has been reported to elevate in chronic renal disease patients, which could promote tubulointerstitial fibrosis and regulate extracellular matrix synthesis and degradation." (PMID 35596156, 2022). "We identified the hub genes of CKD (Fn, Timp1, C3, Apoe, Trf, Fbn1, FGG, Penk, Ckap4, and Gpc3) through multiple bioinformatics analyses and successfully verified their expression in a mouse chronic kidney disease model." (PMID 40564035, 2025). "In a rat model of adenine-induced chronic kidney disease (CKD), adropin was found to reduce urine protein levels and 24-hour urine volume and downregulate inflammatory markers such as TIMP-1, IL-33, and MMP-2, suggesting a protective effect against renal damage and inflammation." (PMID 39766320, 2024). "An early increase in MMP-10 and TIMP-1 was observed and a further progressive elevation was found as DKD progressed to end-stage renal disease." (PMID 31913319, 2020). "Moreover, among patients with chronic renal failure MMP-8, TIMP-1 and MMP-8/TIMP-1 levels had no prognostic impact in SAB." (PMID 34043679, 2021). "However, among patients with chronic renal failure, day 3, day 5 or day 28 MMP-8, TIMP-1 or MMP-8/TIMP-1 had no significant predictive effect on mortality when analyzed by receiver operating characteristic." (PMID 34043679, 2021).
endothelial dysfunction (11 papers, 2009 to 2025). In vascular diseases, endothelial dysfunction is a systemic pathological state of the endothelium (the inner lining of blood vessels) and can be broadly defined as an imbalance between vasodilating and vasoconstricting substances produced by (or acting on) the endothelium. "Higher levels of TIMP1 expression, in the venous endothelial cell and in plasma, are an early sign of endothelial dysfunction." (PMID 27781209, 2016). "Our results emphasized that MMP-9 levels or MMP-9/TIMP-1 ratio could be predictive for endothelial dysfunction." (PMID 34625635, 2021). "TIMP-1 was the only up-regulated gene that directly correlates with endothelial dysfunction." (PMID 30050438, 2018). "In serum samples, we assessed inflammatory markers (IL-1β, TNF-RI, TNF-RII, sFas, sFasL, MMP-9, TIMP-1, and TGF-β1), endothelial dysfunction markers (sE-selectin, sICAM-1, and sVCAM-1), and volume-related marker (NT-proBNP)." (PMID 27034745, 2016).